ATM (ATM serine/threonine kinase)
Diseases named in the same sentence as ATM in open-access papers (continued):
Sharing a sentence is not in itself a finding about the gene and the disease.
tumor (continued). "According to its essential role in the maintenance of genomic stability ATM has been canonically considered a tumor suppressor gene." (PMID 24681585, 2014). "PTEN, a substrate of ATM with functions related in DNA damage repair signalling, also has distinct tumor suppressor roles in modulation of PI3K activity and phosphatidyl inositol signalling." (PMID 24550935, 2014). "Further, BEZ235 has also been shown to possess inhibitory action towards DNA damage response proteins DNA-PK and ATM in multiple tumor models." (PMID 24163230, 2013). "In contrast to miR-18a, expression of ATM was significantly lower in tumors than in non-tumor tissues (p<0.0001), with a median difference of 0.369-fold (IQR 0.127–0.575)." (PMID 23437304, 2013). "Of the 81 significantly regulated miRNAs, the depletion of ATM drove the repression of 4 known miRNA tumor suppressors and the over-expression of 7 known oncomirs." (PMID 23741392, 2013). "The expression of nuclear survivin, DNA-PKcs, Ku70 and ATM was significantly higher in tumor tissues than in normal tissues." (PMID 24066112, 2013). "Combination of PAN with BEZ235 resulted in significant attenuation of the DNA damage repair protein ATM and significantly increased anti-tumor activity compared to each single treatment." (PMID 24163230, 2013). "As senescence has emerged as an important mechanism of tumor suppression and aging, it will be critical to clarify the importance of ATM in different contexts." (PMID 23532176, 2013). "Most excitingly, in both tumor models, significant attenuation of the DNA damage response protein ATM occurred with combination therapy compared to single treatments." (PMID 24163230, 2013). "In tumor tissues, the staining for DNA-PKcs, Ku70 and ATM was predominantly nuclear with minute staining in the cytoplasm." (PMID 24066112, 2013). "The enhanced tumor suppression conveyed by WIP1 loss was only partially bypassed by ATM loss, arguing for a more pleiotropic effect of WIP1 compared to ATM." (PMID 22373487, 2012). "Positive nuclear phospho-S25-53BP1 [phosphorylated 53BP1 (p-53BP1)] expression, representing ATM activity, was observed in 180 of 311 tumours (57.9%)." (PMID 22323184, 2012). "In sum, our results demonstrate a strong oncogenic role for SATB1 in immortalized cells under a permissive gene expression profile and uncover a tumor suppressive role for ATM in preventing SATB1-mediated oncogenesis." (PMID 23251624, 2012). "Previous reports have shown that senescence can be induced by DNA damage in tumor cells through an ATM/ATR dependent mechanism." (PMID 23272087, 2012). "The finding that inhibition of ATM by the small molecule kinase inhibitor KU-55933 has an antiproliferative effect was unexpected in the context of the classic role of ATM as a tumor suppressor gene." (PMID 23185347, 2012). "Logistic regression analysis showed higher expression levels of p-ATM in advanced stage (≥IIb) tumours (OR = 1.851; p = 0.007)." (PMID 22323184, 2012). "Overall, the role of ATM in the execution of the DNA damage response and in the preservation of genomic stability pointed to ATM as a tumor suppressor gene." (PMID 24213315, 2012). "On the other hand, expression of ATM, Ku80, and S6 was significantly higher in well-differentiated tumor tissues than in poorly or moderately differentiated tumor tissues." (PMID 22348039, 2012).
tumor (continued). "ATM IHC revealed nuclear staining of tumor cells, and 15 (48.4%) of 31 cases were positive for ATM staining." (PMID 22485171, 2012). "KU-55933 is a specific inhibitor of the kinase activity of the protein encoded by Ataxia telangiectasia mutated (ATM), an important tumor suppressor gene with key roles in DNA repair." (PMID 23185347, 2012). "The treatment of cultured tumor cells with millimolar concentrations of metformin was found to promote significant activation of ATM, as determined by immunofluorescence microscopy using a monoclonal antibody directed against Ser-1981-phosphorylated ATM." (PMID 22170748, 2011). "Of note, growth retardation and subsequent arrest of A431 tumor cells in response to the chronic energetic stress imposed by continuous exposure to metformin drastically up-regulated ATM activity and ATM protein accumulation." (PMID 22170748, 2011). "We investigated the role of p53Ser18 in the tumor suppressor function of ATM by generating and characterizing compound mutant animals." (PMID 21980358, 2011). "KU-55933 and NU-7026 are two well studied tumor sensitizers that inhibit DSB repair by targeting ATM and DNA-PK, respectively." (PMID 21490922, 2011). "For example, the ATM inhibitor KU-55933 shows high specificity and induces radiosensitizing effects in tumor cells." (PMID 21798026, 2011). "It was obvious that there were a significant difference between the tumors irradiated in combination with the treatment of ATM AS-ODNs and controlling tumor." (PMID 21496344, 2011). "Our present data show that in normal lymphocytes, as well as in cells of tumor lines the level of constitutive ATM activation and γH2AX expression was distinctly attenuated upon exposure to metformin." (PMID 22067284, 2011). "Up-regulating miR-101 efficiently reduced the protein levels of DNA-PKcs and ATM in these tumor cells and most importantly, sensitized the tumor cells to radiation in vitro and in vivo." (PMID 20617180, 2010). "ATM plays an important role in tumor suppression as indicated by the in vivo consequences of ATM deficiency both in human and mice." (PMID 19421407, 2009). "The role of ATM in tumor suppression is solidly established and attributed, at least in part, to its well-known function in DNA damage repair." (PMID 19421407, 2009). "It was found that the tumors irradiated in combination with the treatment of ATM AS-ODNs were effective in controlling tumor growth and showed higher apoptotic rate." (PMID 18950535, 2008). "Stratifying POSH cases by tumour characteristics identified SNPs in FGFR2 and TOX3 associated with ER-positive disease and SNPs in ATM associated with ER-negative disease." (PMID 19094228, 2008). "In contrast with irradiation alone, tumor cell apoptosis was doubled following irradiation in combination with ATM AS-ODNs treatment (Figure." (PMID 18950535, 2008). "Nuclear expression of ATM was found in 91.6% of the tumours, whereas nuclear expression of CHK2 was detected in 66.7% of cases." (PMID 17940507, 2007). "The role of ATM in the self-renewal capacity of hematopoietic stem cells has led to further exploration of other potential ATM-dependent cellular processes such as cell growth, survival, and anti-tumor immune surveillance." (PMID 17487278, 2007).
tumor (continued). "Loss of heterozygosity was identified in four patients and in three of them it was located centromeric to the ATM gene, and, in one, it spanned a large region, indicating the involvement of other tumour-suppressor genes in this disease." (PMID 14735203, 2004). "Both studies identified shared associations: ATM mutations correlated with female sex, smoking history, non-squamous histology (adenocarcinoma), high tumor mutation burden (TMB), and PD-L1 positivity." (PMID 40310425, 2025). "Nonetheless, tumor cells that endure radiation exposure concurrently activate a variety of pro-survival signaling pathways, such as ATM, ATR, AKT, ERK and NF-κB-mediated DNA damage checkpoints, DNA damage repair, inhibition of apoptosis, and cancer stem cell-related stem-like pathways." (PMID 40675967, 2025). "Overall, 16/263 (6.1%) tumour samples had an ATM PV identified." (PMID 40046829, 2025). "ATM plays a key role in CD8+ T cell-mediated tumor immune regulation." (PMID 40825766, 2025). "Radiation activates NF-κB via ATM- or PARP-dependent pathways in both tumor and stromal cells." (PMID 40725389, 2025). "Similarly, low PRDX1/ATM co-expression was associated with better PFS and overall survival (OS) compared to tumours with high PRDX1/high ATM expression." (PMID 40387816, 2025). "In contrast, cyclin D1–overexpressing tumor cells that are ATM proficient may be highly vulnerable to combined POLΘ and ATM inhibition." (PMID 40608419, 2025). "The results showed the PALB2-inactivated tumours to have a predominantly HR-deficient signature (GEL-Ovary_common_SBS3), whereas the ATM-inactivated tumours had a lesser HR-deficiency signature with others (i.e. GEL-Ovary_common_SBS5 and GEL-Ovary_common_SBS1+18) appearing more prominent." (PMID 39794353, 2025). "Inhibiting Chk1 and Chk2, highly conserved serine/threonine kinases and key downstream targets of ATR and ATM, respectively, could disrupt the initiation of G1/S and G2/M checkpoints, impair DNA repair mechanisms and promote apoptosis in tumor cells." (PMID 40422251, 2025). "Additionally, MALAT1 enhances tumor activity by facilitating the dephosphorylation of the ATM protein." (PMID 41141624, 2025). "These mechanistic links suggest that ATM inhibition modulates the inflammatory tumor microenvironment and could potentially influence immune effector function." (PMID 40883442, 2025). "Western blot showed RGC32 knockdown could suppress ATM/ATR/CHK1 pathway and increase the tumor mutational burden (TMB)." (PMID 40740769, 2025). "Further evaluation of the tumor by Caris Molecular Intelligence revealed several mutations, including the NF1 variant of uncertain significance (VUS), NRAS, PBRM1, FAT1, TERT Promoter, and ATM." (PMID 40125165, 2025).
tumor (continued). "This suggests that at least some tumour-suppressive effects of miR-203a-3p may be potentially mediated through ATM targeting." (PMID 41008855, 2025). "Further in-vitro studies of ATM/BRCA1 double heterozygosity led to higher cell transformation rates, delayed recognition of DNA damage, aberrant DNA repair and increased genomic instability which promotes susceptibility to tumour initiation." (PMID 39843919, 2025). "The index patient in family A06 (A06‐01) carried variants in several classical tumor suppressor genes, including two different variants in MLH1 (A441T and the K618A), a variant in PALB2 (L939W) and several variants in ATM and ATR, all classified as VUS or benign." (PMID 40072281, 2025). "Looking at the effect of ATM inhibitor AZD0156 more closely, revealed an upregulation of senescence-associated β-galactosidase in ATMi + RT treated tumor cells, emphasizing the discussed establishment of a strong cell cycle arrest with no detectable colony formation." (PMID 40883442, 2025). "Three of five ATM tumours had biallelic inactivation, with one acquiring a predicted pathogenic somatic missense variant (CADD31 phred score = 26.6, REVEL32 score = 0.558) in a tumour with loss of the variant allele." (PMID 39794353, 2025). "This functional connection with ATM losses could elucidate the observed ANT relationship EPHA2 and ATM mutations across tumor types." (PMID 39160568, 2024). "Radiotherapy could inhibit the growth of tumor cells directly by enhancing cellular stress, and could also amplify the anti-tumor immune effect of ATM inhibition from these two aspects." (PMID 39033176, 2024). "In contrast we do not observe consistently lower (p-)ATM levels in the BAP1-deficient tumour cell lines." (PMID 38519707, 2024). "TMB-L (low tumor mutational load), CCND3 gene acquisition and MRE11A and ATM gene deletion mutations indicated sensitivity to PD-1/PD-L1 inhibitor combinations and the FDA-approved targeted agents Niraparib (Grade C), Olaparib (Grade C), Rucaparib (Grade C) and Talazoparib (Class C)." (PMID 38730456, 2024). "ATM inhibition increases the number of double-strand breaks that will grow in a tumor population since the underlying damage response is not initiated, activating apoptotic signaling after a certain limit of errors has been reached." (PMID 38906870, 2024). "From animal experiments showed that ATM-deficient tumors and ATM inhibitor-treated tumors respond well to radiotherapy and immunotherapy in the typical CRC p-MMR (mismatch repair gene-proficient) tumor model, CT26 tumor model, with the best effect observed in the combination groups." (PMID 39033176, 2024). "Here we show that ceralasertib in combination with anti-PD-L1 demonstrates strong antitumor effects in immunocompetent mouse tumor models, even in the absence of exogenous DNA damage (e.g., IR) or sensitizing tumor molecular alterations (e.g., ATM-loss)." (PMID 38402224, 2024). "Since activation of CD8 positive T cells depends on MHC class I-TCR stimulation signal, we next explored whether ATM inhibition could further activate tumor-infiltrating T cells." (PMID 39033176, 2024). "Thus, BRCA1/2 mutations, along with mutations in other mutator genes like ATM and CHEK2, have been exploited as tumor-agnostic markers, but in a unique application." (PMID 38920700, 2024). "ATM is considered a tumor suppressor and may lead to de novo tumor formation in various tissues when exposed to ATM inhibitors for prolonged periods." (PMID 38910895, 2024). "ATM inhibitor, radiotherapy, and anti–PD-L1 increase systemic tumor control." (PMID 38376927, 2024). "EPHA2 and EP300 mutations consistently show decreased dNdS ratios in the presence of ATM mutation contexts compared to those without ATM mutation contexts across three tumor types, respectively." (PMID 39160568, 2024).
tumor (continued). "In this work, we found that ATM inhibition not only enhanced the sensitivity of tumor cells to radiation but also promoted dsDNA and micronucleus production and STING/type I IFN signaling pathway activation in CRC cells, thus increasing innate immune activation." (PMID 39033176, 2024). "Additionally, the expression of Ku70 and p‐DNA PKcs was suppressed, and DNA damage markers (γ‐H2AX and p‐ATM) accumulated in tumours from Hmga1flox/floxK14 mice." (PMID 39690136, 2024). "The importance of ATM in the maintenance of genomic fidelity and the integrity of the DNA damage repair process suggested that this protein might serve as a tumor suppressor." (PMID 38260227, 2024). "Additionally, ATM is thought to contribute to tumor radioresistance by regulating cell cycle arrest." (PMID 38651153, 2024). "Taking advantage of our multi-omics studies, we further elucidated the mechanism by which PRKDC might promote tumor cell proliferation through its cis-effect and collaborate with ATM and ATR." (PMID 39039072, 2024). "In the PROfound trial, a crossover randomized phase III trial, patients with mCRPC with BRCA1, BRCA2, and ATM tumor alterations showed improved survival when treated first-line with olaparib compared to enzalutamide or abiraterone (19.1 months vs. 14.7 months, HR = 0.69; p = 0.02)." (PMID 38927984, 2024). "Additionally, p‐ATM expression was increased in tumours with HMGA1 knockdown, and the combination of HMGA1 depletion and olaparib treatment further increased p‐ATM levels, suggesting excessive accumulation of DSB damage." (PMID 39690136, 2024). "Our data suggest that a pharmacological inhibition of ATM might be a novel therapeutic option for tumor cells surviving 5-FU." (PMID 35608750, 2023). "Furthermore, we built an easy-to-use nomogram using both clinical (tumour stage and residual disease) and genomic factors (SWI/SNF complex mutations, ATM mutations and chr8q CNAs) to predict the PFS of OCCC." (PMID 37272300, 2023). "Collectively, our findings suggest that Syk drives therapeutic resistance by promoting DNA resection and HR through a novel ATM-Syk-CtIP pathway, and that Syk is a new tumor-specific target to sensitize Syk-expressing tumors to PARPi and other DNA targeted therapy." (PMID 37333340, 2023). "However, it has been found that ATM function is often impaired in tumor cells (from defects in expression, activation, or downstream signaling proteins), resulting in genomic instability, which is advantageous to tumor development." (PMID 37298997, 2023). "OS benefit was greater in patients with tumor lacking ATM mutations, but the difference was not statistically significant." (PMID 35834132, 2023). "Furthermore, ATM gene mutation is found to be correlated with “hot” TIME and increased tumor infiltration of cytotoxic lymphocytes in human endometrial cancers." (PMID 37174688, 2023). "Undoubtedly, ATM signal transduction affects mitochondrial radiation responses in terms of ROS production and control, and this is determining ROS-mediated genomic instability, the tumor microenvironment, and immune responses." (PMID 37511215, 2023). "Moreover, IHC of matched biopsies from one patient before and after BRAFi resistance development showed a clear downregulation of ATM protein levels in the MAPKi resistant tumor compared with the treatment-naïve tumor." (PMID 37674529, 2023). "Afterwards, sensitivity to PARPi has been proved in tumor with loss of other tumor suppressor DNA repair proteins (e.g., ATR, ATM, RAD51, CHEK1/2, and PALB2), suggesting the validity of this therapeutic strategy also in patients intrinsically deficient in HR without BRCA1/2 mutations." (PMID 36793600, 2023).